AKR1C1 (aldo-keto reductase family 1 member C1)
Diseases named in the same sentence as AKR1C1 in open-access papers (continued):
Sharing a sentence is not in itself a finding about the gene and the disease.
tumor (continued). "AKR1C1 interacts with STAT3 and promotes its phosphorylation, so as to promote the expression of downstream-related genes and finally promote tumor metastasis." (PMID 35370661, 2022). "To identify the relationship between AKR1C1 and NSCLC metastasis, we examined AKR1C1 expression in three pairs of clinical NSCLC and corresponding adjacent non-tumor tissue samples." (PMID 35370661, 2022). "In tumorous breast tissues the expression of AKR1C1 and AKR1C2 is reduced promoting tumor growth and progression." (PMID 33593445, 2021). "To determine the clinical relevance of AKR1C1 expression level, we examined AKR1C1 expression in six pairs of clinical NSCLC and corresponding adjacent non-tumor tissue samples." (PMID 34702254, 2021). "Among these ten genes, the expression levels of SETD1B, ACSF2, MUC1, KLHL24, PML, MT1G, and GPT2 were higher in tumor tissues than those in normal tissues, while HIC1, AKR1C1, and LOC390705 were lower expressed in tumor tissues." (PMID 35071242, 2021). "Results showed the expression of AKR1C1 and CARS1 were different in tumor tissues and adjacent tissues." (PMID 34046350, 2021). "Moreover, it has been stated that lowering the expression of AKR1C1 may inhibit proliferation and migration leading to reduction of drug resistance; in particular, Silencing AKR1C1 could suppress tumor growth and invasion, and also decrease the resistance to regular chemotherapy and radiotherapy." (PMID 32327612, 2020). "AKR1B10, AKR1C1, AKR1C2 and AKR1C3 constitute some of the most inducible targets of NRF2 in human systems, both normal and tumour-derived." (PMID 27824809, 2016). "Protein levels of AKR1C1, AKR7A3, and CBR1 significantly correlated with the respective transcript levels assessed by qPCR in the same tumor samples (Spearman ρ = 0.47, P = 0.003, Spearman ρ = 0.61, P < 0.001, and Spearman ρ = 0.44, P = 0.007, respectively)." (PMID 25526449, 2014). "Expression of AKR1C1, AKR1C2, AKR7A3, CYP3A4, and CBR1 was assessed by immunoblotting in protein lysates from tumor tissue samples of the independent pretreatment set of patients." (PMID 25526449, 2014). "Moreover, the AKR1C1+ inflammatory fibroblast strongly expresses IL6 which interacts with IL6R expressed on DC1 and PRR-induced mo-DC, potentially contributing to tumor growth and therapeutic resistance." (PMID 38744958, 2024). "However, they significantly differed in terms of marker genes (AKR1C1, FOSL1, LIF, and THAP2 vs. WNT5A, GREM1, TNC, and MMP1), tissue origins (normal vs. tumor), and organ preferences." (PMID 38744958, 2024). "Moreover, it is known a direct action of NRF2 on proteins involved in chemoresistance such as AKR1C1-3, ABCF2, SLC40A1, as well as on the modulation of important growth factor receptors, such as c-MET, ErbB2 and EGFR regulating tumour growth." (PMID 35453348, 2022). "Consistent with our hypothesis that AKR1C1/2 is a key player in the development of chemoresistance, a significantly shorter PFS was noted for patients expressing AKR1C1/2 in their tumor tissue." (PMID 35115586, 2022). "In addition, AKR1C1 has been confirmed high basal expression levels in CRC and promotes tumor proliferation, metastasis, and drug resistance." (PMID 34249766, 2021). "To analyze AKR1C1 protein expression in these ten pairs of ECC patient samples by immunoblotting (IB) assay, we found that there was elevated expression of AKR1C1 in the majority of human ECC specimens (8 cases/10 cases, 80%), compared with matched non-tumor tissues." (PMID 39478199, 2025). "In this study, we conduct detailed genomic analysis of clinical tumor tissues from a cohort of 75 patients with ECC to identify candidate genes that might contribute to ECC pathogenesis, leading to the discovery of AKR1C1, a member of the AKR gene family, as a crucial player in ECC." (PMID 39478199, 2025). "However, no statistical difference was found between the AKR1C1 expression level and tumor size, age, and gender." (PMID 37173953, 2023).
tumor (continued). "In addition, AKR1C1 can directly interact with and promote phosphorylation of STAT3, enhancing the binding of STAT3 to the promoter regions of target genes, and then transactivating these genes, promoting tumor metastasis." (PMID 36263088, 2022). "AKR1C1 is also a key component for the phosphorylation of STAT3 and it could facilitate the interaction of STAT3 with its upstream kinase JAK2, which promotes tumor metastasis in NSCLC." (PMID 35370661, 2022). "However, under the same experimental conditions, injection of cells expressing AKR1C1 to mice (n = 5) failed to induce tumor." (PMID 26338969, 2015). "Therefore, AKR1C1 would not promote the proliferation of tumor in vivo." (PMID 37173953, 2023). "According to GEPIA in a GBM tumor, there is also increased expression of AKR1B1, decreased expression of AKR1C1 and AKR1C2, and no change in AKR1C3 expression." (PMID 36765904, 2023). "Overall, the median level of AKR1C1, AKR1C2 and AKR1C3 was decreased in tumour, relative to normal tissue but when only mutant cases were considered, all AKRs were significantly increased." (PMID 27824809, 2016). "Consistent with our hypothesis that AKR1C1/2 favors relapse events, a significantly shorter PFS was noted for patients expressing AKR1C1/2 (IRS > 0) in their tumor tissue (median PFS 23.5 vs. 49.6 months, p = 0.013, n = 124)." (PMID 35115586, 2022).
infection (2 papers, 2014 to 2021). The state of being infected such as from the introduction of a foreign agent such as serum, vaccine, antigenic substance or organism. "We found that inflammatory signals, driven by mimics that are widely accepted as representing infection and inflammation, induce AKR1C1 expression through the activation of AP‐1 or NF‐кB TFs." (PMID 34114342, 2021). "The targeted deletion of NF‐кB and AP‐1 consensus sites revealed that NF‐кB mediates infection (LPS)‐induced AKR1C1 transcription, while the AP‐1 pathway is critical for inflammation (TPA)‐induced AKR1C1 transcription." (PMID 34114342, 2021). "Whether it is normal term labour (physiologic inflammation) or infection‐induced PTL, myometrial activation of AP‐1 and/or NF‐кB is observed, and current study suggests that both of these TFs can induce AKR1C1 promoter activity and therefore might contribute to local P4 withdrawal." (PMID 34114342, 2021).
neurodegenerative disease (1 paper, 2015). A disorder of the central nervous system characterized by gradual and progressive loss of neural tissue and neurologic function. "These reactive aldehydes are increased in several neurodegenerative diseases and recombinant AKR1C1–3 have been shown to possess high specific activities against 4HNE." (PMID 25769101, 2015).
prostate (1 paper, 2015). "Taken together, these observations clearly indicate a conjectural role for AKR1C1/ERβ/c-FLIP in prostate pathogenesis that warrants additional investigations to elucidate the regulation of c-FLIP with respect to androgen metabolism and progression to CRPC." (PMID 25816367, 2015).
AKR1C1 also shares sentences with these, for which no sentence is quoted: adenocarcinoma (2 papers); metastatic cancer (2); abdominal aortic aneurysm (1); acute myeloid leukemia (1); allergic disease (1); autism spectrum disorder (1); bladder carcinoma in situ (1); brain glioma (1); chronic lymphocytic leukemia (1); chronic obstructive pulmonary disease (1); congenital adrenal hyperplasia (1); corneal diseases (1); follicular thyroid adenoma (1); head and neck squamous cell carcinoma (1); Hip dysplasia (1); Hypokalemia (1); Insulin resistance (1); leukemia (1); lymphoma (1); metabolic disorders (1); nephropathic cystinosis (1); oropharyngeal tumors (1); osteoporosis (1); psoriasis (1); Simpson-Golabi-Behmel syndrome (1); syndromic (1); T-cell acute lymphoblastic leukemia (1); Tinnitus (1).